CGAS (cyclic GMP-AMP synthase)
Diseases named in the same sentence as CGAS in open-access papers (continued):
Sharing a sentence is not in itself a finding about the gene and the disease.
autoimmune disease (continued). "cGAS is a crucial component of the cGAS–stimulator of interferon gamma (IFN) genes (STING) signalling cascade that is required for the IFN type I response in immune cells, making it an important player in activation of pro‐inflammatory response in autoimmune diseases." (PMID 32715647, 2020). "As understanding on the cGAS-STING pathway deepens, it is realized that excessive activation of this pathway could prolong the expression and secretion of inflammatory cytokines like IFN, leading to autoimmune diseases, such as Aicardi–Goutieres syndrome and lupus." (PMID 38999073, 2024). "Therefore, along with the NLRP3 inflammasome that forms the cGAS/STING/NLRP3 axis in different inflammatory conditions, NLRs negatively regulating the cGLR (cGAS/STING pathway) system have also evolved to protect the host, including humans, from autoinflammatory and autoimmune diseases." (PMID 38339107, 2024). "Hence, dysregulation of these regulatory mechanisms leads to aberrant activation of the cGAS–STING pathway, which induces exaggerated immune responses that lead to sterile inflammatory conditions, including cardiometabolic disorders, neurodegenerative diseases, autoimmune diseases and cancers." (PMID 37175853, 2023). "Suppression of BAF1 increases the accumulation of cGAS within the nucleus and induces a robust IFN response, as noted in the pathogenesis of autoimmune diseases." (PMID 37175853, 2023). "Notably, activation of DNA sensors DNA-PK and AIM2 can also suppress the activation of cGAS, which may be a negative feedback regulation mechanism formed by the immune system to avoid the excessive activation of its innate immune signals and prevent the occurrence of autoimmune diseases." (PMID 36189363, 2022).
melanoma (113 papers, 2016 to 2026). A malignant, usually aggressive tumor composed of atypical, neoplastic melanocytes. "A study shows that STING and cGAS expressions vary in melanoma cell lines and the genes encoding STING and cGAS are frequently epigenetically silenced through promoter hypermethylation, which makes STING signaling non-functional." (PMID 40940791, 2025). "It has been reported that USP18 enhances the resistance of BRAF-mutated melanoma cells to vemurafenib by stabilising cGAS expression and inducing autophagy." (PMID 40374599, 2025). "Consistently, ARID1A deficiency in melanoma and lung cancer increases cytosolic double-stranded DNA fragments, thereby activating the cGAS-STING pathway and potentiating type-I interferon signaling." (PMID 41438758, 2025). "While we have identified interesting trends associated with cGAS expression in melanoma treatment response, our sample size limits the strength of our interpreted association." (PMID 38473384, 2024). "cGAS-deficient mice showed impaired growth of B16 melanomas in response to PD-L1 antibody treatment." (PMID 34830754, 2021). "Loss of STING and/or cGAS was confirmed in some 54% of human colorectal cancer (Stage II-IV) while loss of both was seen in 41.7% of advanced stage human melanoma samples." (PMID 29050360, 2017). "In a study performed by Wang and co-authors, PD-L1 antibody was administered in a mouse model of melanoma and they observed that cGAS-deficient mice are refractory to the antitumor effects of a PD-L1 antibody." (PMID 29050360, 2017). "We considered that, if the frequency of the cGAS protein, instead of mRNA, in omics analysis, were used, the association rate between RSK2 and cGAS in melanoma tissues may higher than the 6.23%." (PMID 39424777, 2024). "However, STING signaling is muted in cancer cells including melanoma cells due to possible mutations in cGAS which converts double stranded DNA into CDNs." (PMID 32477956, 2020). "It is reported that the melanoma response to antitumor immunity is defined by PRMT5 modulation of the cGAS/STING and NLRC5 pathways." (PMID 40777599, 2025). "Taken together, EA6 induces melanoma cells pyroptosis and activates the cGAS-STING signaling pathway in vivo, which demonstrated superior anti-tumor activity." (PMID 41144149, 2025). "For example, USP18 enhances melanoma cell resistance to vemurafenib by stabilising cGAS expression, thereby inducing autophagy." (PMID 40374599, 2025). "When considering all nine patients, the trends observed here suggest that there is a possible positive correlation between cGAS expression in melanoma cells and PFS." (PMID 38473384, 2024). "On the one hand, cGAS-STING pathway plays an anti-tumor role in melanoma, small cell lung cancer, breast cancer and colon cancer by promoting the activation of immune cells, cell apoptosis and tumor vascular remodeling." (PMID 38515746, 2024). "In melanoma‐bearing mice, injected liposomal cGAMP was absorbed by APCs and released into the cytoplasm, where it activated the cGAS–STING signaling pathway." (PMID 38525112, 2024). "On the other hand, cGAS-STING pathway promotes tumor progression in melanoma, breast cancer, lung cancer and skin cancer by promoting tumor immune escape and metastasis and maintaining chronic inflammation." (PMID 38515746, 2024). "Using murine B16-F10 melanoma cells, they found that NF2s with mutations in the FERM domain were potent suppressors of cGAS-STING signaling." (PMID 39796693, 2024). "As previously reported, IFN‐β treatment significantly inhibited the proliferation of the B16‐F10 melanoma cells, whereas knockout of cGAS and IRF3 reversed the inhibitory effects of IFN‐β." (PMID 39004913, 2024). "Our data revealed heightened expression of CD8+ T cell markers (CD8a and CD8b) and NK cell markers (NCR1 and NCR3) in melanoma patients with elevated levels of cGAS/CCL5/CXCL10." (PMID 38506049, 2024).
melanoma (continued). "Our findings reveal a significant survival advantage among melanoma patients with high cGAS expression compared to those with lower cGAS levels." (PMID 38506049, 2024). "While studies in mice support Hippo signaling modulation in NF2-mutant melanomas, studies in humans suggest that NF2-mutant melanomas are more integrally involved in altering the cGas STING signaling pathway." (PMID 39796693, 2024). "The importance of cGAS was further illustrated by the fact that its expression correlates with immune activation and patients’ survival in melanoma." (PMID 37180110, 2023). "Carboplatin activated the cGAS-STING pathway through the upregulation of TREX-1 expression in human melanoma." (PMID 36769349, 2023). "cGAS expression resulted more limited, with positive cells represented by a variable fraction of E2.2+ pDCs, a fraction of melanoma cells and, as expected, infiltrating plasma cells." (PMID 38239354, 2023). "Carboplatin, a second-generation platinum antitumor drug derived from cisplatin, can suppress human melanoma through the activation of cGAS-STING pathway-mediated apoptosis." (PMID 36769349, 2023). "At the same time, researchers have also found that the cGAS-STING signaling pathway is inhibited in various cancer cells ranging from melanoma to ovarian cancer, and colorectal carcinoma." (PMID 35185917, 2022). "In the same melanoma model, cGAS-STING pathway and IFN-I production were necessary to potentiate anti-PD-L1 response, while STING- or cGAS-deficient mice were unable to respond to this therapy." (PMID 34925363, 2021). "To this end, we established Nectin-1, HVEM, STING, and cGAS immunostaining for our panel of 20 melanoma cell lines after embedding them into paraffin." (PMID 34205379, 2021). "Several predictive markers have been proposed in in vitro and in vivo models, amongst them the cyclic GMP-AMP synthase (cGAS) with the stimulator of interferon genes (STING) as a recognition pattern of cytosolic HSV DNA in malignant melanoma." (PMID 34205379, 2021). "Taken together, these data confirm the suppressive function of carboplatin in human melanoma proliferation through cGAS/STING pathway activation." (PMID 34519260, 2021). "Recently, it has been identified that the use of demethylating agents can enhance cGAS/STING expression in silenced melanoma cell lines." (PMID 34372614, 2021). "The current investigation postulated that carboplatin can suppress human melanoma through the activation of the cGAS-STING pathway via TREX-1 upregulation." (PMID 34519260, 2021). "The hypermethylation of cGAS/STING promoters was initially implicated in a pair of studies analyzing the role of STING in colorectal cancer and melanoma cell lines." (PMID 34372614, 2021). "The presence of considerable CpG islands within the STING and cGAS promoter regions contributes to the epigenetic regulation of STING in melanoma cells." (PMID 34830754, 2021). "To evaluate the role of STING and cGAS in our panel of melanoma cell lines, we studied the expression of both molecules using Western blot analysis with respect to the housekeeping protein ß-actin." (PMID 34205379, 2021). "They further go on to demonstrate that deletion of cGAS in both normal cell lines and murine melanoma cell lines that cGAS is essential for DNA damage-induced senescence (etoposide and radiation)." (PMID 34884568, 2021). "In established human melanoma cell lines, the cGAS/STING pathway is frequently dysfunctional and cannot be activated by cytosolic DNA." (PMID 32978520, 2020). "Nevertheless, cGAS has been reported to be essential for the response to immune checkpoint blockade in B16 mouse melanoma studies." (PMID 30240750, 2018). "Similar studies in melanoma cell lines have shown loss of STING in 3/11 lines and of cGAS (the synthase generating cyclic dinucleotides) in 4/11 lines." (PMID 30240750, 2018).
melanoma (continued). "Baseline expression levels of ISGs and genes associated with the cGAS-STING signaling pathway were investigated in both melanoma models, but these did not correlate with differential outcomes to combination therapies." (PMID 38312842, 2024). "Moreover, in RSK2 and cGAS association analysis, we found that cGAS and RSK2 association was observed in 6.23% among 36.4% of RSK2-associated melanoma cells." (PMID 39424777, 2024). "MnP treatment activated the cyclic guanosine monophosphate-adenosine monophosphate synthase-stimulator of interferon genes (cGAS-STING) pathway in murine melanoma cells (B16-F10), as confirmed by real-time quantitative polymerase chain reaction (RT-qPCR) and western blotting (WB) analysis." (PMID 38994034, 2024). "Furthermore, we show that most liver cancer cells express cGAS, but hardly express STING, in HCC samples, consistent with previous reports showing loss of cancer cell-intrinsic STING in melanoma and colorectal cancer." (PMID 38177099, 2024). "However, it has been reported that PRMT5 down-regulates cGAS-mediated antiviral immune response or type I IFN response in a melanoma mouse model." (PMID 38838142, 2024). "In addition to aneuploidy status, we also compared cGAS expression in melanoma cells to the PFS of our patient cohort." (PMID 38473384, 2024). "However, the cGAS–STING pathway is inhibited in human skin cutaneous melanoma, resulting in reduced melanoma IFN‐I production and loss of tumor antigenicity, characteristics that are essential for melanoma immune evasion." (PMID 38525112, 2024). "Notably, in melanoma, the endogenous activation of the cGAS-STING was limited to areas of spontaneous microscopic melanoma regression with a large number of tumor-infiltrating pDCs suggesting their activation." (PMID 39020402, 2024). "Moreover, we also confirmed that colony growth of malignant melanoma cells in anchorage-independent condition was dramatically increased in the stably cGAS overexpressing cells by EGF or bFGF stimulation." (PMID 39424777, 2024). "Next, we utilized a melanoma xenograft model to investigate whether the cGAS‐STING‐IRF3 axis is involved in IFN‐β‐triggered antitumor activity." (PMID 39004913, 2024). "In addition, we also observed a similar relationship between Vhl-KO and activation of the cGAS-STING pathway in B16F10 melanoma cells." (PMID 39050705, 2024). "Interestingly, reports of cGAS expression in other tumor types are variable with both up- and down-regulation demonstrated in colon cancer, melanoma, and ovarian cancer." (PMID 37079538, 2023). "In a recent study on melanoma, using genome-wide DNA methylation profiling, investigators showed that promoter hypermethylation of the cGAS and STING genes mediates their coordinated transcriptional silencing and contributes to the widespread impairment of the STING signaling function." (PMID 35267494, 2022). "Interestingly, nuclear membrane rupture was frequent in the marginal region of footpad tumors, and consistent with this, cGAS-positive nuclear blebs and micronuclei were observed at a higher frequency in the margin of human plantar melanoma samples." (PMID 35468978, 2022). "In both studies, a wide range of cGAS/STING expression levels in melanoma cell lines was observed." (PMID 34205379, 2021). "The present investigation hypothesized that carboplatin activates the cGAS-STING pathway through the upregulation of the TREX-1 expression in human melanoma." (PMID 34519260, 2021). "Interestingly, previous work has suggested that melanomas with low MTAP have decreased cGAS-STING signaling, and MTAP is often co-deleted/silenced with CDKN2A." (PMID 33550279, 2021). "Targeting of TREX1/cGAS/STING pathway could be an effective therapeutic alternative to human melanoma." (PMID 34519260, 2021). "Thus, NRF2-dependent suppression of innate immune response genes can occur in human melanoma cells with a functional cGAS/STING pathway." (PMID 32978520, 2020).
melanoma (continued). "We examined STING and cGAS expression in a panel of human melanoma cell lines by immunoblot." (PMID 30400822, 2018). "Immunoblot analysis revealed a diverse STING/cGAS expression status in human melanoma cell lines." (PMID 30400822, 2018). "This impairment of the cGAS-STING innate immune response could contribute to the prevalence of β-HPV infections.IMPORTANCEBeta human papillomaviruses (β-HPVs) may promote non-melanoma skin cancers in certain immunocompromised populations by destabilizing the host genome." (PMID 41744906, 2026). "Targeting the TREX1/cGAS-STING signaling axis could be a potential therapy for human melanoma." (PMID 37163421, 2023). "Herein, we demonstrate that APS suppresses melanoma growth and prolongs survival by inducing immunogenic cell death (ICD) via the cGAS-STING pathway." (PMID 41981755, 2026). "This is consistent with our previous findings and supported by studies reporting cGAS and/or STING dysregulation in colorectal cancer, ovarian cancer, Merkel cell carcinoma, and melanoma." (PMID 40830678, 2026). "The activation of cGAS-STING promotes neutrophil accumulation and enhances CD8+ T cell-mediated anti-tumor immunity in breast cancer and melanoma." (PMID 40786100, 2025). "PRMT5 methylates IFN-γ inducible protein 16 (IFI16) and suppresses NLRC5 transcription, inhibiting the cGAS-STING and MHCI pathways in melanoma, thereby weakening IFN signaling and antitumor immune responses." (PMID 40166469, 2025). "Altogether, we uncover that both pharmacological and siRNA‐mediated VPS34 inhibition in RCC and melanoma cells activates the type I IFN and proinflammatory cytokine response via induction of the cGAS‐STING pathway." (PMID 38506049, 2024). "To analyse the RSK2-cGAS signaling pathway in cell transformation, we established JB6 Cl41 and SK-MEL-2 malignant melanoma cells stably overexpressing cGAS." (PMID 39424777, 2024). "Apart from cGAS/STING activation, toll-like receptor 9 (TLR9) and absence in melanoma 2 (AIM2) initiate responses to cytosolic DNA." (PMID 38990864, 2024). "Furthermore, we established a subcutaneous B16-F10 melanoma model for intratumoral BCG treatment and compared wild type mice to TLR2-/-, TLR3-/-, TLR4-/-, TLR7-/-, TLR3/7/9-/-, caspase 1-/-, caspase 11-/-, IL-1R-/-, cGAS-/-, STING-/-, IFNAR-/-, MyD88-/-deficient animals." (PMID 38835781, 2024). "Elevated PRMT5 (protein arginine methyltransferase 5), a component of the cGAS/STING pathway, has been correlated with prolonged survival among patients with melanoma and decreased melanoma growth in murine models." (PMID 38473384, 2024). "Based on a set of microscopic, functional and in silico analyses, we demonstrated that the melanoma milieu directly impairs IFN-α and CXCL10 production by pDCs via TLR-7/9 and cGAS-STING signaling pathways." (PMID 38239354, 2023). "Carboplatin activates the cGAS-STING pathway by upregulating TREX1 expression to inhibit proliferation and induce apoptosis in melanoma cells." (PMID 37163421, 2023). "In melanoma tumor cells, CARM1 ablation induced dsDNA breaks and cGAS-STING activation, together with the increased expression of several ISGs, including Irf7, Ifit1, Oasl1, and Tap1, and the enhancement of tumor cell susceptibility to cytotoxic T cells." (PMID 35493527, 2022). "TREX1 is downregulated in human melanoma, overexpression of TREX1 induces apoptosis and decreases proliferation in human melanoma cancerous cell lines, TREX1 overexpression activates the cGAS/STING pathway to induce apoptosis and decrease cell growth." (PMID 34519260, 2021). "As one of the strategies for melanoma development, STING is suppressed in melanoma cells by epigenetic silencing of STING and cyclic GMP-AMP synthase, possibly due to suppressed DNA hypermethylation in melanoma cells." (PMID 34830754, 2021). "The findings reported that carboplatin activates TREX1 and cGAS/STING, leading to the suppression of proliferation in human melanoma." (PMID 34519260, 2021).